VAMP7 (vesicle associated membrane protein 7)
Diseases named in the same sentence as VAMP7 in open-access papers:
VAMP7 is named in the same sentence as 34 diseases in open-access papers, as found by Europe PMC text mining. Sharing a sentence is not in itself a finding about the gene and the disease. The quoted sentences say what the papers report.
gastric cancer (3 papers, 2022 to 2025). A primary or metastatic malignant neoplasm involving the stomach. "To verify whether NR2F1-AS1 promotes GC progression by regulating the expression of VAMP7, we first investigated the expression of VAMP7 in normal and stomach cancer tissues." (PMID 35082283, 2022). "In gastric cancer, NR2F1-AS1 enhances cell growth through various axes, including miR-29a/VAMP7, miR-190a/PHLDB2/AKT3, SPI1/ST8SIA1, and miR-493-5p/MAP3K2." (PMID 40828427, 2025). "In gastric cancer, NR2F1-AS1 acts as an EMT-inducing lncRNA that enhances cell motility via the miR-29a/VAMP7 axis, activation of AKT3 through miR-190a/PHLDB2, SPI1-mediated transcriptional upregulation of ST8SIA1, and miR-493-5p/MAP3K2 signaling." (PMID 40828427, 2025). "Moreover, lncRNA NR2F1-AS1 promotes GC progression through miR-29a-3p/VAMP7 axis, which may be related to EMT progression in gastric cancer." (PMID 38698487, 2024).
autism (2 papers, 2017 to 2022). Persistent deficits in social interaction and communication and interaction as well as a markedly restricted repertoire of activity and interest as well as repetitive patterns of behavior. "Interestingly, knockdown of H2A.Z.1, but not H2A.Z.2, led to altered expression of several candidate genes linked to psychiatric disorders such as autism and schizophrenia (Neurexin1, Shank3, CaMK2G, Vamp7, Gsk3b, Tuba8, Grm8, etc.)." (PMID 28856239, 2017).
cervical cancer (2 papers, 2023 to 2026). A primary or metastatic malignant neoplasm involving the cervix. "Vesicle‐associated membrane protein 7 (VAMP7) plays a pivotal role in HPV16‐driven cervical cancer by regulating autophagy, promoting tumour cell survival, immune evasion and lesion progression." (PMID 41508736, 2026). "Association between vesicle‐associated membrane protein 7 (VAMP7) expression and clinicopathological characteristics of patients with cervical cancer (CC)." (PMID 41508736, 2026). "Functionally, VAMP7 enhanced proliferation, migration, and invasion while inhibiting apoptosis in cervical cancer cells, whereas distinct effects were observed in non‐tumor cervical epithelial cells." (PMID 41508736, 2026). "In addition, syntaxin‐4, SNAP‐23, and VAMP‐7 play equivalent roles in exosome secretion in both HeLa cervical cancer cells and A375 melanoma cells, suggesting their conserved function in exosome secretion." (PMID 37700095, 2023). "VAMP7 may represent a potential therapeutic target for the treatment of cervical cancer." (PMID 41508736, 2026). "VAMP7 demonstrated dynamic expression changes during cervical lesion progression, characterized by decreased expression in HPV16‐positive non‐malignant tissues and a gradual increase with disease severity, reaching the highest levels in advanced cervical cancer." (PMID 41508736, 2026).
cyst (2 papers, 2014 to 2021). A sac-like closed membranous structure that may be empty or contain fluid or amorphous material. "The effects of VAMP7 depletion on ciliogenesis and cystogenesis are not directly linked to the disruption of lysosomal function, as cilia lengths and cyst morphology were unaffected in an MDCK lysosomal storage disorder model." (PMID 24466086, 2014).
hepatocellular carcinoma (2 papers, 2021 to 2023). A malignant tumor that arises from hepatocytes. "The abnormal lncRNA LINC00511 induces formation of invadopodia by regulating the colocalization of VAMP7 and synaptosome associated protein 23 (SNAP23) and is thus involved in tumor progression as shown in hepatocellular carcinoma (HCC) cells." (PMID 35008434, 2021).
melanoma (2 papers, 2016 to 2023). A malignant, usually aggressive tumor composed of atypical, neoplastic melanocytes. "(2013) showed that depletion of strumpellin from MNT‐1 melanoma cells caused a missorting of BLOC‐1 cargoes ATP7A and VAMP7 to the plasma membrane." (PMID 27390154, 2016).
tetanus (2 papers, 2021). A serious infectious disorder that follows wound contamination by the Gram-positive bacterium Clostridium tetani. "While it has been proposed that specific tetanus-insensitive VAMP proteins (such as VAMP7) are involved in the release of exosomes into the extracellular space, we cannot exclude the additional contribution of other types of vesicles to the observed phenotype." (PMID 34038402, 2021).
airway hyperresponsiveness (1 paper, 2018). "Therefore, VAMP-7 mediates eosinophil degranulation both in vitro and ex vivo, and this event augments airway hyperresponsiveness." (PMID 30271964, 2018).
Anxiety (1 paper, 2019). Intense feelings of nervousness, tension, or panic often arise in response to interpersonal stresses. "At the 3′ end of this selected region, VAMP7 codes for a protein which localizes to late endosomes and lysosomes and is involved in the fusion of transport vesicles to their target membranes; a knock‐out of VAMP7 exon 3 caused reduced brain weight and anxiety in mice." (PMID 30945415, 2019).
asthma (1 paper, 2018). "Here we sought to determine the role of VAMP-7-mediated eosinophil degranulation in allergic airway inflammation as an important exacerbatory event in asthma." (PMID 30271964, 2018). "This study suggests VAMP7 as a therapeutic target for ameliorating asthma." (PMID 30271964, 2018).
breast carcinoma (1 paper, 2023). "In this study, we identified syntaxin‐4, SNAP‐23, and VAMP‐7 as the SNAREs responsible for exosome secretion in MCF‐7 breast cancer cells and found that a SNARE complex consisting of these SNAREs can drive membrane fusion in vitro." (PMID 37700095, 2023). "In this study, we identified syntaxin‐4, SNAP‐23, and VAMP‐7 as the cognate SNAREs that mediate exosome secretion in MCF‐7 human breast cancer cells." (PMID 37700095, 2023). "Furthermore, the deletion of VAMP‐7 in 4T1 murine mammary carcinoma cells significantly restrained the growth and metastasis of tumour in vivo." (PMID 37700095, 2023). "Furthermore, deletion of VAMP‐7 in 4T1 mammary carcinoma cells efficiently inhibited exosome secretion and led to significant attenuation of tumour growth and lung metastasis in mouse models, implying that VAMP‐7 may hold promise as a novel therapeutic target for breast cancer." (PMID 37700095, 2023).
breast tumour (1 paper, 2023). "In our study, we established a tumour‐bearing mice model and found that breast tumour growth was suppressed and the quantity of serous sEVs was reduced in the tumour‐bearing mice inoculated with VAMP7‐deleted 4T1 cells." (PMID 37700095, 2023).
chronic myeloid leukemia (1 paper, 2023). "In addition, other studies found that VAMP‐7, but not VAMP‐3, is essential for exosome secretion in K562 human chronic myeloid leukemia cells, which aligns with our identification of VAMP‐7 as the R‐SNARE that mediates exosome secretion in tumour cells." (PMID 37700095, 2023).
esophageal cancer (1 paper, 2021). A primary or metastatic malignant neoplasm involving the esophagus. "Vesicle-Associated Membrane Protein 7 (VAMP7) is a member of the synaptobrevin family which was found to be highly expressed and associated with a shorter survival period in esophageal cancer which could act as a dangerous gene." (PMID 34238288, 2021).
glioblastoma (1 paper, 2026). The most malignant astrocytic tumor (WHO grade IV). "VAMP7 knockout glioblastoma cells implanted in male rat brain develop into more necrotic tumors with reduced macrophage infiltration compared to controls, suggesting that VAMP7-dependent late endosomal secretion contributes to the tumor microenvironment and affects macrophage infiltration." (PMID 41723185, 2026).
lentivirus infection (1 paper, 2017). Virus diseases caused by the Lentivirus genus. "In order to assess the impact of these vesicular SNAREs on synaptic efficacy, we cultured rat hippocampal neurons and used vti1a and VAMP7 short hairpin RNA (shRNA) expression via lentivirus infection to reduce vti1a and VAMP7 protein levels." (PMID 28186166, 2017).
leukemia (1 paper, 2023). A malignant (clonal) hematologic disorder, involving hematopoietic stem cells and characterized by the presence of primitive or atypical myeloid or lymphoid cells in the bone marrow and the blood. "Moreover, although VAMP7, a well-known late endosomal and lysosomal R-SNARE, has been shown to promote exosome release from human leukemia K562 cells, VAMP7 inhibition has been reported not to affect exosome release from epithelial Madin-Darby canine kidney (MDCK) cells." (PMID 37704453, 2023).
lung carcinoma (1 paper, 2024). "SNAREs like VAMP7 in the human leukemic cell line (K562), YKT6 in human embryonic kidney cells (HEK293) and human lung cancer cells (A549) were found to be the vesicular SNAREs involved in fusion." (PMID 39619685, 2024).
multiple myeloma (1 paper, 2022). "Recently, it was reported that system Xc− mediated glutamate export enhanced exosome secretion in multiple myeloma and bone marrow stromal cells by upregulating the expression of Rab27a, TSG101, Alix, and VAMP7, thereby contributing to bortezomib resistance in multiple myeloma." (PMID 36320056, 2022).
neuroblastoma (1 paper, 2023). Neuroblastoma (NB) is the most common solid, extracranial childhood tumor. "Since these studies were performed in non-neuronal HeLa cells, we decided to explore the distribution of VAMP7-coated vesicles in neuroblastoma-derived SH-SY5Y cells as a proxy of their neuronal function." (PMID 38139155, 2023). "Therefore, we compared the effects of the two human VAMP7 isoforms in neurite outgrowth assays on transfected neuroblastoma-derived SH-SY5Y human cells." (PMID 38139155, 2023).
typhoid (1 paper, 2022). "Collectively, these results indicate that the last step in typhoid toxin export is controlled by the VAMP7/SNAP23/STX4 SNARE complex, which targets the typhoid toxin vesicle carrier intermediates for fusion to the plasma membrane and subsequent release of the toxin cargo to the extracellular space." (PMID 35579416, 2022).
viral infection (1 paper, 2025). "However, we found that viral infection was not influenced by VAMP7 knockdown, a R-SNARE protein that governs the heterotypic fusion between late endosomes and lysosomes, which appears to contradict the result of the RAB7 depletion experiment." (PMID 39746094, 2025).
tumor (12 papers, 2015 to 2026). "In xenograft models, VAMP7 overexpression significantly promoted tumor growth and increased the expression of autophagy‐associated markers." (PMID 41508736, 2026). "In this context, we assessed the clinical value of 8 genes (RAB2B, RAB3B, RAB9A, RAB11B, RAB27A, RAB27B, STX1A, and VAMP7), which are implicated in sEVs biogenesis, as well as their association with overall and tumor-derived plasma sEVs levels." (PMID 36980570, 2023). "Importantly, these clinical observations are concordant with our in vitro and in vivo findings, in which VAMP7 overexpression promoted tumour growth, invasion and autophagy‐associated phenotypes." (PMID 41508736, 2026). "However, VAMP7 was up-regulated in high -risk group and this implied it was a tumor-promoting role." (PMID 32998713, 2020). "VAMP7 knockdown significantly suppressed tumour growth, as evidenced by reduced tumour volume and weight compared to the control group." (PMID 41508736, 2026). "Further studies are needed to fully elucidate the molecular mechanisms by which VAMP7 regulates autophagy and its interplay with the tumour microenvironment, providing valuable insights into potential therapeutic strategies for CC." (PMID 41508736, 2026). "Transmission electron microscopy of tumour tissues confirmed the in vivo autophagy regulation, showing fewer autophagosomes in the VAMP7 shRNA group and more autophagosomes in the VAMP7 overexpression group." (PMID 41508736, 2026). "The biphasic expression pattern of VAMP7 suggests its dual role in CC progression—tumour‐suppressive in early disease and tumour‐promoting in advanced stages." (PMID 41508736, 2026). "In contrast, VAMP7 overexpression significantly accelerated tumour growth, leading to larger and heavier tumours." (PMID 41508736, 2026). "Elevated VAMP7 expression was associated with advanced FIGO stage, lymphovascular invasion and tumour recurrence." (PMID 41508736, 2026). "In other words, during the current ceRNA network, NR2F1-AS1 and VAMP7 played oncogenic roles in GC, while increasing studies have reported that miR-29a-3p exerted tumor-suppressive roles in GC." (PMID 35082283, 2022). "VAMP7 is known to play functional roles in cancer biology, as it is required for invadopodium formation and tumor cell invasion in diverse cancer types." (PMID 27589845, 2016). "In non‐tumour cells, VAMP7 knockdown impaired autophagy and led to increased apoptosis, while in cancer cells, VAMP7 overexpression enhanced autophagosome formation, cell proliferation, migration and invasion, promoting tumour progression." (PMID 41508736, 2026). "As cervical lesions advance, increasing metabolic and invasive demands may promote the upregulation of VAMP7 to support tumour survival and metastasis." (PMID 41508736, 2026). "Given its involvement in autophagy and tumour progression, VAMP7 may represent a potential therapeutic target for HPV‐related CC." (PMID 41508736, 2026). "VAMP7's differential effects on cancerous and non‐cancerous cells suggest that it may act as a modulator of autophagy in the tumour microenvironment, promoting cancer cell survival and invasion while inhibiting these processes in non‐malignant cells." (PMID 41508736, 2026). "High VAMP7 expression was significantly correlated with FIGO stage, lymphovascular invasion and recurrence (p < .05), supporting its association with aggressive tumour behaviour." (PMID 41508736, 2026). "Additionally, IHC revealed decreased LC3B expression in the VAMP7 shRNA group and increased LC3B expression in the VAMP7 overexpression group, further confirming that VAMP7 regulates autophagy during tumour progression." (PMID 41508736, 2026). "In addition, significant reduction of SNAP23, VAMP7, and NLRC5 proteins indicates the reduction of cancer-associated protein trafficking, unconventional secretome, and tumor growth." (PMID 37941832, 2023).
tumor (continued). "Interestingly, this correlation analysis showed that mainly in the ICD clinical settings tumoural CALR levels positively correlated with the tumoural levels of phagocytosis-associated genes (especially PLA2G5, PLD1, RAB5A, VAMP7, STAB2)." (PMID 26314964, 2015). "Importantly, syntaxin‐4, SNAP‐23, and VAMP‐7 were also found to mediate exosome secretion in other types of tumour cell lines, for example, HeLa and A375 cells, suggesting their functional importance and conservation in exosome secretion across diverse tumour types." (PMID 37700095, 2023). "This broader relevance places VAMP7 at the intersection of HPV‐related and HPV‐independent mechanisms, linking autophagy, vesicular trafficking and tumour adaptation during cervical carcinogenesis." (PMID 41508736, 2026). "VAMP7 is downregulated in early‐stage HPV16‐positive lesions (HPV16+ LSIL), suggesting a potential tumour‐suppressive role early in the disease." (PMID 41508736, 2026). "The latest research confirmed that VAMP7 is involved in MT1-MMP+ MVB membrane trafficking, further regulating the production of invadopodia to maintain the aggressiveness of tumor cells." (PMID 34088337, 2021). "Interestingly, VAMP7 is not only upregulated in HPV16‐positive CC but also in HPV18‐positive and HPV‐negative tumours, indicating that the role of VAMP7 in autophagy regulation extends beyond HPV16‐associated lesions." (PMID 41508736, 2026). "Additionally, we found BECN1, DAPK1, VAMP7 and SIRT1 genes were correlated significantly with survival status, gender, primary tumor and tumor stage (all P < 0.05)." (PMID 32998713, 2020). "However, VAMP7 expression increases significantly in advanced lesions (HPV16+ HSIL and HPV16+ CA), which aligns with the shift of autophagy from tumour suppression to tumour promotion as the disease progresses." (PMID 41508736, 2026).
infection (7 papers, 2020 to 2026). The state of being infected such as from the introduction of a foreign agent such as serum, vaccine, antigenic substance or organism. "induces phagocytotic entry into the host cells by using VAMP8 at the entry site; recruits VAMP2, VAMP3, and VAMP4 on to the Salmonella-containing vacuoles during infection; and uses VAMP7 for secretion of typhoid toxins outside the host cell." (PMID 39950824, 2025). "VAMP7 knockdown attenuated cell growth and increased cell apoptosis relative to the control 96 hours after infection." (PMID 36860654, 2023). "In a previous work we studied the recruitment of the SNARE proteins VAMP3 and VAMP7 to the parasitophorous vacuole of T. cruzi CL Brener strain at different times after infection." (PMID 33194787, 2020). "We also observed a similar kinetics of association displayed by these proteins although the transit in the vacuole was slower than the previously observed for CL Brener strain showing the peak of VAMP7 recruitment at 6 h after infection." (PMID 33194787, 2020). "In that work we established that formation of the vacuole is extended up to 1 h after infection followed by vacuole maturation which was characterized by the arrival and fusion of VAMP7 and Lamp1-positive vesicles and vacuole acidification from 1 h to around 6 h after infection." (PMID 33194787, 2020). "VAMP7 and Vti1B were localized to the PVM within 30 min post-infection, suggesting potential roles during invasion, while VAMP8 and Stx7 appeared later around 24 h post infection (hpi), coinciding with increased nutrient acquisition." (PMID 41972675, 2026).
cancer (6 papers, 2016 to 2026). A tumor composed of atypical neoplastic, often pleomorphic cells that invade other tissues. "This dynamic expression trend implies that VAMP7 may participate in the progression from high‐grade lesions to carcinoma during HPV16‐driven cervical neoplasia." (PMID 41508736, 2026). "The alteration frequencies in cancer cell lines were as follows: CDKN1A (4%), DNAJB9 (6%), GABARAPL1 (5%), RAB1A (1.6%), and VAMP7 (0.6%), with amplification being the most common type of alteration." (PMID 41040512, 2025). "VAMP7 upregulation is not restricted to HPV16‐related cancers, supporting the idea that its role in autophagy regulation could be a shared feature of CC progression, rather than being specific to one HPV genotype." (PMID 41508736, 2026). "With this procedure, we recorded about 100 STED platelet images each, for six different proteins (VAMP7, VAMP8, STX11, SNAP23, TSP1, and VEGF) and for five different categories of platelets; incubated with cancer cells (MCF-7, MDA-MD-231, EFO-21), non-cancer cells (MCF-10A), or no cells at all (R)." (PMID 35729633, 2022).
VAMP7 also shares sentences with these, for which no sentence is quoted: cystinosis (1 paper); diabetes (1); hypospadias (1); inflammation (1); lung adenocarcinoma (1); lysosomal storage disorder (1); psychiatric disorder (1); schizophrenia (1); stomach cancer (1).